PIGR (polymeric immunoglobulin receptor)
Description:
[Polymeric immunoglobulin receptor]: Mediates selective transcytosis of polymeric IgA and IgM across mucosal epithelial cells. Binds polymeric IgA and IgM at the basolateral surface of epithelial cells. The complex is then transported across the cell to be secreted at the apical surface. During this process, a cleavage occurs that separates the extracellular (known as the secretory component) from the transmembrane segment. [Secretory component]: Through its N-linked glycans ensures anchoring of secretory IgA (sIgA) molecules to mucus lining the epithelial surface to neutralize extracellular pathogens. On its own (free form) may act as a non-specific microbial scavenger to prevent pathogen interaction with epithelial cells.
Tractability: Small molecule: it has a high-quality binding pocket. Antibody: UniProt places it where antibodies can reach, with high confidence; its Gene Ontology location is reachable by antibodies, with high confidence; UniProt predicts a signal peptide or a membrane-spanning region.
Gene: Protein-coding gene on chromosome 1 (206,928,522 to 206,949,367, reverse strand). Ensembl gene ENSG00000162896.
Subcellular location: Cell membrane (Polymeric immunoglobulin receptor); Secreted (Secretory component)
Pathways (Reactome):
Immune System: Neutrophil degranulation
Gene Ontology:
Molecular function: polymeric immunoglobulin binding; polymeric immunoglobulin receptor activity; protein binding; transmembrane signaling receptor activity
Biological process: detection of chemical stimulus involved in sensory perception of bitter taste; epidermal growth factor receptor signaling pathway; Fc receptor signaling pathway; immunoglobulin transcytosis in epithelial cells mediated by polymeric immunoglobulin receptor; receptor clustering; signal transduction
Cellular component: extracellular exosome; extracellular region; plasma membrane; receptor complex; secretory IgA immunoglobulin complex; azurophil granule membrane; bounding membrane of organelle; cytoplasmic vesicle membrane; endomembrane system
Genetic constraint (gnomAD): Loss-of-function variants: 23 observed, 74.34 expected, observed/expected ratio (o/e) 0.31, 90% interval 0.22 to 0.44. The upper end of that interval is the gene's LOEUF score, 0.44, which puts it in group 1 of 6, group 1 being the genes least tolerant of losing a copy. Missense variants: 885 observed, 1,022.8 expected, observed/expected ratio (o/e) 0.87, 90% interval 0.82 to 0.92. Synonymous variants: 413 observed, 423.84 expected, observed/expected ratio (o/e) 0.97, 90% interval 0.9 to 1.06.
Homologues: Orthologues: chimpanzee PIGR (98% identical), macaque PIGR (89% identical), dog PIGR (69% identical), pig PIGR (68% identical), guinea pig PIGR (68% identical), mouse Pigr (66% identical), rat Pigr (59% identical), rabbit PIGR (55% identical). Paralogues in human: FCAMR (15% identical), CD300LG (9% identical), FCMR (9% identical), TREML1 (8% identical), CD300LF (7% identical), CD300A (6% identical), CD300E (6% identical), CD300LB (6% identical), CD300C (6% identical), CD300H (5% identical), CD300LD (5% identical), TMIGD3 (5% identical), and 1 more.
Diseases named in the same sentence as PIGR in open-access papers:
PIGR is named in the same sentence as 143 diseases in open-access papers, as found by Europe PMC text mining. Sharing a sentence is not in itself a finding about the gene and the disease. The quoted sentences say what the papers report.
hepatocellular carcinoma (22 papers, 2014 to 2025). A malignant tumor that arises from hepatocytes. "It has been suggested that the polymeric immunoglobulin receptor encoded by the PIGR gene stimulates activation of the ribosomal pathway in hepatocellular carcinoma." (PMID 40724830, 2025). "The expression of PIGR is associated with the prognosis of gastric adenocarcinoma, esophageal carcinoma, endometrial carcinoma, hepatocellular carcinoma, and other tumors." (PMID 36505781, 2022). "Consistent with our data from ELISA analysis, downregulation of pIgR is associated with the development of most lung cancers, adenocarcinomas of distal oesophagus and gastro-oesophageal junction, and hepatocellular carcinoma." (PMID 25652121, 2015). "To date, we are only aware of one study reporting adverse prognostic implications of pIgR expression in human cancer, namely in hepatitis B-derived hepatocellular carcinoma, where high pIgR expression was found to be associated with a greater metastatic potential and poor prognosis." (PMID 25397670, 2014). "However, contradicting data was reported in a study on hepatitis B-derived hepatocellular carcinoma, where high PIGR expression was found to be associated with greater metastatic potential and poor prognosis." (PMID 24694107, 2014). "Specifically, the identification of pIgR in serum EVs of hepatocellular carcinoma (HCC) patients is linked to enhancing cancer stemness in HCC cells, thereby contributing to the initiation and progression of liver cancer." (PMID 39062561, 2024). "Increased PIGR expression has also been observed in the gastrointestinal tract and hepatocellular carcinoma." (PMID 39284282, 2024). "PIGR expression in hepatocellular cancer, colon cancer, pancreatic cancer, osteosarcoma and glioma has been shown to correlate with poor prognosis." (PMID 37789066, 2023). "Increasing PIGR expression can promote cell proliferation in hepatocellular carcinoma cells but can inhibit cell proliferation in lung cancer." (PMID 37789066, 2023). "Mechanistically, PIGR promotes hepatocellular carcinoma by activating the Smad and Yes-MEK/ERK signaling pathways." (PMID 35992840, 2022). "Polymerized immunoglobulin receptor (PIGR) plays an oncogenic role in hepatocellular carcinoma through activation of ribosomal pathways." (PMID 36434693, 2022). "Mechanistically, PIGR promotes tumor growth and metastasis in hepatocellular carcinoma and pancreatic cancer, whereas PIGR inhibits tumor proliferation in lung cancer." (PMID 35992840, 2022). "Our previous publication revealed that PIGR was overexpressed in tumor tissues compared to adjacent tissues in hepatocellular carcinoma." (PMID 33937393, 2021). "Of note, contrasting results, supporting a tumour-promoting role for pIgR, have been described in a comprehensive translational study on hepatocellular carcinoma (HCC), where high pIgR expression was found to be associated with early recurrence and chronic hepatitis B-virus (HBV)-infection." (PMID 25397670, 2014). "For instance, PIGR can promote the tumorigenesis and metastasis of hepatocellular carcinoma (HCC)." (PMID 40386563, 2025). "Moreover, increasing the expression of PIGR in hepatocellular carcinoma cells can induce epithelial mesenchymal transition (EMT) of cancer cells and lead to tumour metastasis." (PMID 37789066, 2023). "Previous studies have shown that PIGR is upregulated in several malignancies, such as hepatocellular carcinoma and osteosarcoma, and is downregulated in other cancers, including pancreatic cancer, breast cancer, ovarian cancer, and stomach and esophageal cancer." (PMID 35992840, 2022). "In hepatocellular carcinoma, PIGR-loaded extracellular vesicles could activate Akt/GSK3β/β-catenin signaling cascades, driving cancer stemness, tumorigenesis, and metastasis." (PMID 36157233, 2022). "Upregulation of pIgR has been identified in colon cancer, breast cancer, endometrial carcinoma, bladder carcinoma and hepatocellular carcinoma (HCC)." (PMID 24699841, 2014).
hepatocellular carcinoma (continued). "Key cancer-related pathways such as “Gastric cancer”, “Hepatocellular carcinoma” and “Proteoglycans in cancer” were prominently identified in network, bar and bubble plots, and genes such as NME1, PSAT1, AHCY and PIGR were significantly involved." (PMID 40567612, 2025). "For example, tumor cells derived from hepatocellular carcinoma secreted elevated levels of RasGAP SH3 structural domain binding protein (G3BP) and polymeric immunoglobulin receptor (PIGR) contained in EVs." (PMID 39530097, 2024). "Previous studies revealed a pro-oncogenic role of PIGR in hepatocellular cancer by activating Src family tyrosine kinase (Yes) and MEK/ERK signaling, while PIGR in breast cancer was rarely reported." (PMID 32047513, 2019). "Although PIGR has been proven to promote hepatocellular carcinoma aggressiveness, the role of PIGR in breast cancer is not clear." (PMID 36243728, 2022). "Additionally, PIGR is recognized as a negative prognostic biomarker that may facilitate tumor progression in hepatocellular carcinoma and pancreatic ductal adenocarcinoma." (PMID 40386563, 2025).
breast carcinoma (19 papers, 2013 to 2025). "High polymeric immunoglobulin receptor (PIGR) expression in breast cancer is associated with an improved 5-year survival rate." (PMID 40584290, 2025). "In our study, we identified that the differentially expressed genes of PIGR are predominantly enriched within immune-related annotations and pathways associated with breast cancer (BRCA)." (PMID 40386563, 2025). "To elucidate the potential mechanisms underlying the inhibitory effects of PIGR on breast cancer proliferation, we leveraged the TCGA database to identify DEGs associated with PIGR expression." (PMID 40386563, 2025). "High expression of polymeric immunoglobulin receptor (PIGR) in breast cancer is associated with increased 5-year survival rate." (PMID 36207349, 2022). "Increased PIGR expression in vivo in breast cancer could reflect tumor-associated immune cells' polarized condition." (PMID 40584290, 2025). "The increased expression of PIGR in breast cancer might reflect the polarization of tumor-associated immune cells." (PMID 37154982, 2023). "Conversely, overexpression of PIGR not only inhibited the proliferation and cloning of breast cancer cells but also suppressed their migration." (PMID 40386563, 2025). "Our analysis indicated that the methylation level of the PIGR promoter was significantly higher in primary breast cancer (BRCA) tissues compared to normal breast tissues." (PMID 40386563, 2025). "The results showed that PIGR expression was significantly downregulated in breast cancer tissues compared to adjacent normal tissues." (PMID 40386563, 2025). "To further substantiate these findings, we employed IHC staining to evaluate PIGR expression in breast cancer tissues and corresponding normal tissues from 18 breast cancer patients." (PMID 40386563, 2025). "We confirmed the establishment of MCF-7 breast cancer cell lines with stably upregulated PIGR expression through Western blotting." (PMID 40386563, 2025). "PIGR can suppress breast cancer cell growth in vitro and in vivo and is an independent protective factor for BRCA patients’ prognosis." (PMID 40386563, 2025). "Specifically, we compared gene expression profiles between high and low PIGR expression groups in breast cancer patients and identified a total of 531 DEGs.This cohort included 190 up-regulated DEGs (35.8%) and 341 down-regulated DEGs (64.2%)." (PMID 40386563, 2025). "Further in-depth investigation into the role of PIGR in tumor immunity is expected to provide a more comprehensive understanding of the mechanisms by which PIGR affects the development of breast cancer." (PMID 40386563, 2025). "In the future, We plan to explore the molecular mechanism of PIGR and other breast cancer biomarkers and integrate them to improve prediction accuracy." (PMID 40386563, 2025). "In breast cancer, PIGR is shown to be downregulated in tumor tissues compared to normal tissue, and high PIGR expression is strongly associated with better cumulative survival compared to low PIGR levels." (PMID 39770537, 2024). "The role of PIGR in cell proliferation in these breast cancer cell lines is in agreement with its role in endometrial cancer cells, in which alteration of PIGR does not affect cell proliferation." (PMID 37789066, 2023). "The present study aimed to investigate the effect of PIGR expression on breast cancer cell lines with regard to chemosensitivity, cell viability and cell proliferation." (PMID 37789066, 2023). "The findings from the present study demonstrated different levels of PIGR expression in distinct subtypes of breast cancer cells." (PMID 37789066, 2023). "This indicated that both the breast cancer cell lines studied naturally possess a low level of PIGR expression." (PMID 37789066, 2023). "We have previously shown that IL-1β was the M1 macrophage cytokine which enhanced PIGR expression in breast cancer cells and that IFNγ also increased PIGR expression." (PMID 37789066, 2023).
breast carcinoma (continued). "Given the absence of IFN-γ expression in M1 polarized macrophages, we assessed the ability of IL-1β, which was robustly upregulated in M1 polarized cells, to increase PIGR expression in breast cancer cells." (PMID 36207349, 2022). "The effect of increasing the concentration of IL-1β on PIGR expression and secretory component secretion in breast cancer cells was further investigated." (PMID 36207349, 2022). "IL-1 receptor blockade assay using IL-1 receptor antagonist (IL-1RA) was performed to confirm the action of IL-1β secreted from M1 macrophages on the expression of PIGR in breast cancer cells." (PMID 36207349, 2022). "A gene signature of luminal breast cancer indicated that PIGR served as one biomarker for good outcome." (PMID 36243728, 2022). "In the present study, the effect of macrophages and their polarization on PIGR expression in breast cancer cell lines, was investigated." (PMID 36207349, 2022). "The aim of this study was to determine the role of macrophages and cytokines affecting expression of PIGR in two breast cancer cell lines." (PMID 36207349, 2022). "There is, however, no documentation regarding the regulatory factors that influence PIGR expression in breast cancer." (PMID 36207349, 2022). "This study also provided evidence that IFN-γ had a similar effect to IL-1β on increasing PIGR expression in breast cancer cells." (PMID 36207349, 2022). "An AA metabolic signature (SPINK8, KLRB1, APOD and PIGR) was constructed for breast cancer prognosis." (PMID 36243728, 2022). "This study also suggests that high PIGR expression is a biomarker for better OS and Its role in breast cancer progression appears to be entirely different from that of liver cancer, while the conclusion should be supported by more evidence." (PMID 36243728, 2022). "The immune function-related genes CD300LG and PIGR were also detected as downregulated in breast cancer." (PMID 31182966, 2019). "Paraffin sections from 36 different breast cancer tumours were stained for IgA1, Tn antigen, pIgR and HPA." (PMID 23637900, 2013). "Our results suggest that PIGR overexpression may enhance the ability of breast cancer cells to present antigens to CD8+T cells, potentially counteracting the immune evasion mechanism of HLA class I downregulation." (PMID 40386563, 2025). "CCK-8 proliferation and colony formation assay demonstrated that overexpression of PIGR could inhibit breast cancer cell proliferation, clone formation, and migration." (PMID 40386563, 2025). "IFN-γ and IL-1β both boosted the expression of PIGR in breast cancer cells." (PMID 40584290, 2025). "Several studies have indicated that PIGR has prognostic value in breast cancer." (PMID 39770478, 2024). "Nevertheless, the functions of PIGR in breast cancer should be further investigated." (PMID 39770478, 2024). "The result showed that IL-1β but not IFN-γ mRNA was highly expressed in M1 macrophages, suggesting that IL-1β may be an M1 macrophage cytokine involved in PIGR upregulation in breast cancer cells." (PMID 36207349, 2022). "Breast cancer was one of the earliest cancers shown to express PIGR." (PMID 36207349, 2022). "Elevated PIGR expression in breast cancer in vivo may reflect the polarization state of tumor-associated immune cells." (PMID 36207349, 2022). "The levels of PIGR mRNA expression in the breast cancer cells were evaluated by RT-qPCR." (PMID 36207349, 2022). "This present study demonstrated a previously unknown interplay between macrophages and breast cancer cells, regarding M1 macrophages enhancing PIGR expression in breast cancer cells through IL-1β." (PMID 36207349, 2022). "Moreover, the PIGR expression is downregulated in breast cancer tissues compared with paracancerous tissues." (PMID 36243728, 2022). "PIGR overexpression in breast cancer was shown to be related with favorable outcome." (PMID 36207349, 2022). "PIGR is known to be upregulated in breast cancer and other cancers." (PMID 33892787, 2021).
breast carcinoma (continued). "pIgR has been reported to be overexpressed in colon and breast cancer, endometrial carcinoma, bladder carcinoma, and HCC; however, the clinical significance of pIgR remains unknown." (PMID 24699841, 2014). "To investigate whether the PIGR affects the expression of genes encoding some key immunomodulatory molecules, we extracted RNA from MCF-7 breast cancer cell lines with PIGR overexpression and control cell lines, and detected the expression of these genes by qPCR." (PMID 40386563, 2025). "These imply that the complexity of PIGR regulation in vivo is likely to involve the coordination of various immunomodulatory factors and that the elevation of PIGR expression in breast cancer in vivo may reflect the polarization state of tumor-associated immune cells." (PMID 36207349, 2022). "PIGR overexpression could suppress cell proliferation and adhesion in breast cancer cells." (PMID 36157233, 2022). "Therefore, this may indicate that PIGR is a marker of M1 macrophages only in certain breast cancer subtypes (basal-like subtype)." (PMID 36207349, 2022). "Furthermore, the expression level of PIGR in breast cancer cells may be a surrogate marker of M1 macrophage infiltration in the TME." (PMID 36207349, 2022). "Finally, 6 upregulated DEGs (CST2, DRP2, CLEC5A, SCD, KIAA1211, DTL) and 6 downregulated DEGs (STAC2, BTNL9, CA4, CD300LG, GPIHBP1 and PIGR), were confirmed in a quantitative real time PCR comparison of breast cancer and paracancerous breast tissues from 8 clinical specimens." (PMID 31182966, 2019). "Our study constructed the prognostic signature based on breast cancer PD-1/PD-L1 pathway molecular typing-related genes (IFNG, JCHAIN, ELOVL2, PIGR, PAGE5, ACTL8, and CLEC3A)." (PMID 37154982, 2023). "M1, M2 macrophage conditioned media (CM) and recombinant human cytokines were used to determine factors which increased PIGR expression in MCF7 (HTB-22) and MDA-MB468 (HTB-132) breast cancer cell lines." (PMID 36207349, 2022). "The assumption is that PIGR per se does not affect cellular behaviour and chemosensitivity of these breast cancer cell lines in 2D cell culture." (PMID 37789066, 2023). "They used Western blotting to examine PIGR protein expression in five breast cancer cell lines, MCF7, MDA-MB231, Hs578T, SK-BR-3 and ZR-75-1, and in a normal breast cell line (Hs578Bst) and found that PIGR protein was barely detected in any of the cell lines tested." (PMID 37789066, 2023). "PIGR per se did not affect cellular behaviours and chemosensitivity of these breast cancer cell lines." (PMID 37789066, 2023). "For some of the breast cancer tumours studied here, a correlation was seen between the staining intensity, or lack of staining, between pIgR and IgA1 in the cancer cells." (PMID 23637900, 2013). "However, the functional role of PIGR in breast cancer cells has not been elucidated." (PMID 37789066, 2023). "However, the factors influencing PIGR expression in breast cancer have not been elucidated." (PMID 36207349, 2022).